INS (insulin)
Diseases named in the same sentence as INS in open-access papers (continued):
Sharing a sentence is not in itself a finding about the gene and the disease.
Insulin resistance (continued). "Some of these processes are related to inhibition of insulin signaling pathway resulting in insulin resistance, reduced insulin gene expression and consequently reduced insulin secretion by beta cells." (PMID 25104975, 2014). "With the increase in adipose tissue fat deposits, as in obesity, the ability of insulin to stimulate glucose transport and metabolism in adipocytes and skeleton muscle is impaired resulting in insulin resistance." (PMID 24868532, 2014). "Whole grain and legume consumption is known to decrease insulin resistance or insulin demand and improve lipid profiles, including decreasing triglyceride levels." (PMID 24775272, 2014). "The delivery of insulin into hepatocytes is decreased and chronic hyperinsulinemia occurs together with inadequate beta cell response and peripheral/hepatic insulin resistance." (PMID 25295519, 2014). "In contrast, the insulin resistance that accompanies uncontrolled Type 1 diabetes is primarily attributed to glucotoxicity and is reversible with insulin therapy in vivo." (PMID 25330241, 2014). "Significant differences have been observed in insulin resistance, fasting glucose and plasma insulin between the groups after 8 weeks." (PMID 25560330, 2014). "This appears to be part of the Asian Indian phenotype which includes increased plasma insulin levels, insulin resistance, increased waist circumference, excess visceral fat and low adiponectin levels." (PMID 24817067, 2014). "Here insulin resistance was measured by the euglycemic-hyperinsulinemic clamp, which represents the gold standard for the evaluation of insulin sensitivity, and the results were confirmed by finding increased fasting insulin concentrations." (PMID 24853141, 2014). "Insulin resistance or insulin sensitivity were estimated using the homeostatic model assessment-insulin resistance (HOMA-IR), and the Quantitative Insulin Sensitivity Check Index (QUICKI) methods." (PMID 25247153, 2014). "The examination of the biological mechanisms through which sTWEAK improves insulin sensitivity has demonstrated that, in visceral adipocytes, treatment with sTWEAK ameliorates TNFα-induced insulin resistance on glucose uptake." (PMID 24565471, 2014). "Plasma insulin levels were assessed from the mice after a 3-hr fast, which along with fasting blood glucose levels comprise a homeostatic model assessment of insulin resistance (HOMA-IR) value and is indicative of insulin sensitivity." (PMID 24910707, 2014). "There are currently two classes of drugs available to treat insulin resistance, thiazolidinediones and metformin; new insulin sensitizers are required." (PMID 25360162, 2014). "Both inflammation and prednisolone induced insulin resistance as insulin secretion was strongly increased whereas blood glucose concentrations and hepatic glucose production were only slightly decreased." (PMID 25181348, 2014). "HOMA-IR and QUICKI are based on the feedback loop of glucose and insulin in the post-absorptive state and thus are more representative of hepatic insulin resistance and hepatic glucose output." (PMID 24555815, 2014). "For example, a recent study showed that BMI, insulin, and insulin resistance assessed through the homeostasis model assessment (HOMA) correlated significantly with adiponectin levels only in Caucasian women." (PMID 24575123, 2014). "HOMA-IR is based on the dynamic interaction between glucose and insulin output and is a well-documented clinical representation of insulin resistance when compared to the gold standard reference, the euglycemic clamp." (PMID 24447392, 2014). "Collectively, our findings suggest that with statin use, HDL, LDL and total cholesterol levels can predict performance on executive function; and both peripheral insulin and insulin resistance can predict performance on attention." (PMID 24816647, 2014).
Insulin resistance (continued). "Insulin resistance is characterized by a decrease in the ability of insulin to stimulate the use of glucose by muscles and adipose tissues and to suppress hepatic glucose production and output." (PMID 25136362, 2014). "Chronic overnutrition creates chronic hyperglycemia that can gradually induce insulin resistance and insulin secretion impairment." (PMID 25019091, 2014). "As expected, the distribution of the level of insulin resistance/sensitivity indicators was significantly different between the two groups (all p < 0.0001, except for glucose/insulin ratio (p = 0.016)." (PMID 24447396, 2014). "The development of glucose tolerance disorders in adults involves insulin resistance and impaired insulin secretion." (PMID 24979613, 2014). "Hyperglycemia after GDM pregnancy results from beta cell failure and inability to compensate the increased insulin resistance by insulin secretion." (PMID 25174260, 2014). "Another important therapeutic target in T2D patients should be a reduction in insulin resistance (e.g., with diet, exercise, and/or drug therapy) and/or a stimulation in insulin secretion." (PMID 25071725, 2014). "As T2D is characterized by a combination of peripheral insulin resistance and impaired insulin secretion, the study provides further support for the potential application of the FXR agonists in the prevention of T2D." (PMID 24872814, 2014). "Experimental mice model of hepatic Sirt1 deficiency displayed hyperglycemia, glucose intolerance, hepatic insulin resistance, and oxidative stress in insulin-sensitive organs through disrupted mTorc2/Akt signaling." (PMID 25346724, 2014). "Accordingly, insulin tolerance tests in GlcN-treated mice revealed a limited degree of insulin resistance at specific time points, whereas the corresponding areas under the curve were different by trend only." (PMID 24714520, 2014). "While the anti-inflammatory role of IL-1Ra in the pancreas is well established, the role of IL-1Ra in other insulin target tissues and the contribution of systemic IL-1Ra levels to the development of insulin resistance remains to be defined." (PMID 25244011, 2014). "For example, transgenic mice expressing multiple copies of the insulin gene, although lean and normoglycemic, exhibited marked insulin resistance." (PMID 25259572, 2014). "Women with PCOS show higher insulin resistance but also larger insulin secretion to maintain normal glucose homeostasis than age-, BMI- and insulin resistance-matched controls." (PMID 24705280, 2014). "This indicates that the more the site of injection was exposed to subcutaneous insulin, the more severe the picture of insulin resistance was." (PMID 24711924, 2014). "Type 2 diabetes displays the phenotype of hyperglycemia which results from insulin resistance and impaired insulin secretion." (PMID 25133699, 2014). "Insulin resistance (IR) is a state during which a higher than normal insulin level is required for glucose homeostasis." (PMID 25257559, 2014). "In conclusion, we believe that early and more accurate BCF assessment can be achieved with the use of methods that provide an index of insulin secretion that takes into consideration the degree of insulin resistance in each individual." (PMID 24524730, 2014). "An insulin resistance index (glucose (mM) x insulin (ng/ml)) was calculated and it was significantly lower in both groups of mice on PUFA HFD than in those on SAT HFD." (PMID 25541716, 2014). "The QUICKI is a useful assessment of insulin sensitivity, correlating closely with Euglycaemic Hyperinsulinaemic Clamp (a gold standard assessment of insulin resistance) across a wide range of glucose and insulin concentrations." (PMID 24885899, 2014). "Multiple studies indicate that chronic exposure to insulin leads to insulin resistance, with dramatic increases in mortality from multiple diseases." (PMID 24949486, 2014). "HFD-induced obesity exhibited high glucose, insulin, TG and cholesterol in the blood, and insulin resistance." (PMID 24991305, 2014).
Insulin resistance (continued). "Comparison of predictive ability of tissue-specific insulin resistance indices with fasting plasma insulin levels at baseline in predicting worsening of hyperglycemia at the 5.9-years METSIM follow-up study, Kuopio, Finland." (PMID 25310839, 2014). "Ser-312 phosphorylation is important in insulin resistance and has negative regulation of insulin signaling." (PMID 25580119, 2014). "We go on to quantify many of the N- and O-glycan structures between insulin responsive and insulin resistance conditions demonstrating no significant changes in complex glycosylation in the time frame for the induction of insulin resistance." (PMID 24948903, 2014). "Individuals with a higher VAI category had lower insulin sensitivity (P<0.001) and greater insulin resistance (P<0.001)." (PMID 25105797, 2014). "And what more important was that overexpression of miR-492 effectively reduced the medium glucose and insulin concentrations, indicating an improvement role of miR-492 in insulin resistance." (PMID 24526524, 2014). "We have previously shown that obese animals and humans display insulin resistance in the brain which translates to alterations in hepatic gluconeogenesis, insulin sensitivity in the periphery, locomotor activity and finally glucose disposal." (PMID 24643026, 2014). "Here we find that female mice perinatally exposed to low doses of DDT and subsequently fed a HFD in adulthood developed impaired glucose tolerance, increased fasting insulin, and HOMA-IR, indicative of insulin resistance and increased risk for T2D." (PMID 25076055, 2014). "Given that obesity often causes metabolic syndrome, such as hyperglycemia and peripheral insulin resistance, we measured fasting glucose and insulin levels in Ptprt+/+ and Ptprt−/− littermates." (PMID 24949727, 2014). "Insulin resistance was assessed by an oral glucose tolerance test, an insulin tolerance test, and by measurement of plasma glucose and insulin levels." (PMID 24781986, 2014). "Insulin resistance is the main pathogenic event in T2DM and is characterized by a failure of tissues to respond to insulin, leading to a reduction in glucose uptake by peripheral tissue and increased hepatic glucose output." (PMID 24918297, 2014). "Insulin resistance, a key feature of obesity, is a state in which the sensitivity of target cells to respond to ordinary levels of insulin is reduced." (PMID 24797416, 2014). "Second, glycemic control is affected by both the level of insulin secretion and the degree of insulin resistance." (PMID 25349635, 2014). "This incretin response has been suggested to be impaired in type 2 diabetes (T2D), characterized by hyperglycemia resulting from impaired insulin production and insulin resistance in peripheral tissues, as a result of reduced postprandial GLP-1 concentrations." (PMID 25028601, 2014). "At the initial stage, peripheral insulin resistance increases demands of insulin secretion to stabilize blood sugar, which requires increased insulin transcription and translation." (PMID 25628604, 2014). "Insulin resistance develops in insulin-responsive tissues due to the aberrant accumulation of intracellular lipids including the sphingolipid ceramide." (PMID 25071723, 2014). "Calculated indices reflecting insulin resistance or both insulin resistance and insulin secretory capacity showed their substantial ability to predict future type 2 diabetes." (PMID 24587359, 2014). "In profoundly insulin resistant ob/ob animals, cinnamon promoted tyrosine phosphorylation of the insulin receptor in liver tissues (insulin-stimulated PY-IR: 61.3±3.3 vs. 35.4±5.3 arb." (PMID 24643026, 2014). "The most important physiological components of T2D are insulin resistance, which is characterized by impaired response to insulin in insulin-sensitive tissues, and β-cell failure, which is characterized by β-cell dysfunction and reduced β-cell mass." (PMID 25167060, 2014).
Insulin resistance (continued). "A significant inverse association was found between IGF-1 and insulin levels, as well as between IGF-1 levels and insulin resistance index (HOMA-IR)." (PMID 24586785, 2014). "Type 2 diabetes (T2DM) is by far the most common form of the disease, resulting from a combination of impaired insulin production and insulin resistance in peripheral tissues." (PMID 24872354, 2014). "The most probable reason for this contradictory phenomenon is that the infused WJ-MSCs rapidly improved general insulin resistance, which led to a reduction in endogenous insulin secretion and the need for exogenous insulin injection." (PMID 24759263, 2014). "Since adipocyte insulin resistance was induced by either indirectly (HG + INS) or directly (LG + PUGNAc) altering O-GlcNAc levels, it is likely that O-GlcNAc is modulating the secretion of these adipocytokines." (PMID 25657638, 2014). "GDM is characterized by a relatively diminished insulin secretion coupled with a pregnancy-induced insulin resistance." (PMID 25132852, 2014). "Defects in autophagy have been shown to reduce insulin sensitivity in the liver of obese mice with insulin resistance and hyperinsulinemia." (PMID 24474199, 2014). "T2DM is the result of peripheral insulin resistance, which leads to insulin dysregulation and hyperglycemia." (PMID 25071557, 2014). "Previous reports using metabolic syndrome animal models have shown that astaxanthin reduces insulin resistance, recovers insulin sensitivity, and increases serum levels of adiponectin." (PMID 25515685, 2014). "Type 2 diabetes usually starts from increased insulin resistance, a disorder that cells cannot respond to insulin normally and the pancreas gradually loses its ability to generate enough insulin." (PMID 24852786, 2014). "Several evidences have shown that chronic activation of intracellular pro-inflammatory pathways within insulin target cells can lead to obesity-related insulin resistance." (PMID 24481132, 2014). "Patients with T2DM are characterized by insulin resistance, which results in high circulating insulin concentrations, and increased growth factors’ production." (PMID 25501064, 2014). "The conferred insulin resistance is so far ascribed to interference with insulin signaling, and the possibility that C2-ceramide also inhibits GLUT4 sorting has been neglected." (PMID 24705014, 2014). "Prior work in rodents has shown diet-induced obesity induces insulin resistance in rat brain and that testosterone replacement improves insulin sensitivity in obese rats." (PMID 25224590, 2014). "Fasting serum glucose, insulin and homeostatic model assessment insulin resistance (HOMA-IR, 4.40 ± 0.8 vs. 1.19 ± 0.2) were significantly higher in patients with NASH (all p < 0.001)." (PMID 24962805, 2014). "It was demonstrated that CTB-APSL fusion protein was able to effectively promote insulin secretion and to improve insulin resistance in type 2 diabetic mice." (PMID 24633252, 2014). "HCV genotype 1b evokes insulin resistance by direct influence on intracellular insulin signaling pathway or by indirect mechanisms related with metabolic disturbances." (PMID 25121101, 2014). "Clinical characteristics, glucose, insulin, insulin resistance, lipids, transaminases, and thyroid hormones in 1854 subjects." (PMID 24595410, 2014). "Insulin resistance is defined as the diminished ability of cells or tissues to respond to the physiological concentrations of insulin." (PMID 24910800, 2014). "It is interesting to note that two metabolites with opposing roles, 5-HEPE (insulin secretion) and d18∶1–22∶0 Cer (insulin resistance), are concurrently increased with age in healthy males." (PMID 24632803, 2014). "A recent study demonstrated that high consumption of low fat dairy lowered fasting insulin by 9% and insulin resistance by 11% in obese individuals." (PMID 24956949, 2014).
Insulin resistance (continued). "Recent studies have shown that systemic insulin resistance contributes to dysregulated insulin and metabolic signaling in the heart and the development of diastolic dysfunction." (PMID 24521405, 2014). "Exercise improves insulin sensitivity in diet-induced insulin resistance primarily by restoration of HISS-mediated glucose uptake." (PMID 26237598, 2014). "More direct evidence of HDL improving insulin resistance in humans is provided in a study showing infusion of rHDL particles increases plasma insulin levels, and decreases plasma glucose levels in type 2 diabetic subjects." (PMID 24347528, 2014). "Obesity has many deleterious physiological effects like cellular energy imbalances that can result in impairment of insulin secretion and the development of insulin resistance." (PMID 26237395, 2014). "In some metabolic disorders, such as T2D, cells fail to respond to the normal actions of insulin, resulting in insulin resistance." (PMID 25214711, 2014). "As expected, the distribution of the level of insulin resistance/sensitivity indicators was significantly different between the two groups all P < 0.0001, except for glucose/insulin ratio (P = 0.0304)." (PMID 25197274, 2014). "Nicotine is also found to induce insulin resistance and to decrease insulin release by pancreatic beta cells." (PMID 24783225, 2014). "It has become increasingly obvious that insulin resistance and the efforts made by the insulin-targeted organs to compensate for this defect play a vital role in the pathogenesis and clinical course of the metabolic syndrome." (PMID 24485020, 2014). "High-fat intake generally increases TG and FFA, which can result in insulin resistance by impaired insulin secretion and glucose production." (PMID 25053966, 2014). "For instance, even with significant insulin resistance as determined by serum glucose levels, insulin was able to activate SREBP-1c and promote lipogenesis." (PMID 25371775, 2014). "In general, chronic hypercortisolism blocks or impedes the action of insulin on peripheral tissues, such as liver, muscle and adipose tissue, leading to increased insulin resistance, and it partially inhibits insulin release by the pancreatic beta-cells." (PMID 23564338, 2014). "Palmitate treatment showed reduced Akt phosphorylation in response to insulin (P < 0.01) hence indicated development of insulin resistance." (PMID 24892004, 2014). "The insulin tolerance test results indicated that insulin resistance developed in HFD rats compared with control rats." (PMID 25436770, 2014). "Insulin resistance is the prediabetic state where insulin sensitive tissues such as muscles, adipocytes, and liver show reduced sensitivity towards insulin and a decreased glucose uptake (GU), which leads to elevated blood-glucose levels." (PMID 25254050, 2014). "In this study, the measurement of fasting serum levels of glucose and insulin (indices of insulin resistance) indicated that the male pups from PFOS-exposed maternal groups showed significantly greater serum insulin levels than the control pups." (PMID 24498028, 2014). "The degree of obesity modifies the relationships among insulin resistance, insulin secretion and insulin catabolism such that plasma glucose and insulin concentrations are better able to delineate differences in more obese individuals." (PMID 24555815, 2014). "Peripheral insulin resistance and hyperinsulinemia have a counterintuitive impact on insulin levels within the central nervous system." (PMID 25071557, 2014). "The β-cell mass expands to adapt to the progressive insulin resistance and insulin secretion increases to maintain normal blood sugar levels during pregnancy and the postpartum period." (PMID 25105792, 2014). "Insulin resistance can be defined as a subnormal state of biological responses to circulating insulin." (PMID 24714992, 2014).